DCUN1D3 (defective in cullin neddylation 1 domain containing 3)
Description:
Contributes to the neddylation of all cullins by transferring NEDD8 from N-terminally acetylated NEDD8-conjugating E2s enzyme to different cullin C-terminal domain-RBX complexes and may play a role in the cell cycle progression by regulating the SCF ubiquitin E3 ligase complex, after UV damage. At the cell membrane, can promote and as well inhibit cullins neddylation.
Synonyms: DCNL3; SCCRO3; MGC48972; FLJ41725; DKFZp686O0290; 44M2.4
Tractability: Antibody: UniProt places it where antibodies can reach, with high confidence; its Gene Ontology location is reachable by antibodies, with high confidence. PROTAC: ubiquitination databases record sites on it; its protein half-life has been measured; a small molecule that binds it is known.
Gene: Protein-coding gene on chromosome 16 (20,854,897 to 20,900,400, reverse strand). Ensembl gene ENSG00000188215.
Subcellular location: Cell membrane; Cytoplasm; Nucleus; Cytoplasm, perinuclear region
Subcellular location (Human Protein Atlas): Cytosol; Nucleoplasm
Pathways (Reactome):
Metabolism of proteins: Neddylation
Gene Ontology:
Molecular function: cullin family protein binding; protein binding; ubiquitin conjugating enzyme binding; ubiquitin-like protein binding
Biological process: negative regulation of cell growth; negative regulation of G1/S transition of mitotic cell cycle; negative regulation of protein neddylation; positive regulation of apoptotic process; positive regulation of protein neddylation; regulation of cell cycle process; regulation of protein neddylation; response to gamma radiation; response to UV-C; protein neddylation
Cellular component: cytoplasm; cytosol; nucleoplasm; nucleus; perinuclear region of cytoplasm; plasma membrane; ubiquitin ligase complex
Genetic constraint (gnomAD): Loss-of-function variants: 6 observed, 25.73 expected, observed/expected ratio (o/e) 0.23, 90% interval 0.13 to 0.46. The upper end of that interval is the gene's LOEUF score, 0.46, which puts it in group 2 of 6, group 1 being the genes least tolerant of losing a copy. Missense variants: 258 observed, 394.05 expected, observed/expected ratio (o/e) 0.65, 90% interval 0.59 to 0.73. Synonymous variants: 120 observed, 151.22 expected, observed/expected ratio (o/e) 0.79, 90% interval 0.68 to 0.92.
Homologues: Orthologues: chimpanzee DCUN1D3 (99% identical), macaque DCUN1D3 (99% identical), rabbit DCUN1D3 (98% identical), guinea pig Dcun1d3 (98% identical), rat Dcun1d3 (98% identical), mouse Dcun1d3 (98% identical), dog DCUN1D3 (97% identical), pig DCUN1D3 (97% identical), tropical clawed frog dcun1d3 (78% identical), rat Dcun1d3 (72% identical), zebrafish dcun1d3 (62% identical), Drosophila melanogaster SCCRO3 (37% identical). Paralogues in human: DCUN1D1 (33% identical), DCUN1D2 (33% identical), DCUN1D4 (25% identical), DCUN1D5 (21% identical).
Diseases named in the same sentence as DCUN1D3 in open-access papers:
DCUN1D3 is named in the same sentence as 7 diseases in open-access papers, as found by Europe PMC text mining. Sharing a sentence is not in itself a finding about the gene and the disease. The quoted sentences say what the papers report.
COVID-19 (2 papers, 2022 to 2023). A disease caused by infection with severe acute respiratory syndrome coronavirus 2. "A higher level of IFI27 with a lower level of DCUN1D3 is said to increase the risk for COVID-19." (PMID 37685932, 2023). "On the other hand, 450 (22.96%) and 63 (41.18%) DEGs were downregulated (Down) in COVID-19 patients and recovered subjects, respectively, and of them, only 12 genes (i.e., MAFF, ARHGEF12, DCUN1D3, DR1, MT-CO1)." (PMID 36059456, 2022).
psoriasis (1 paper, 2025). An autoimmune condition characterized by red, well-delineated plaques with silvery scales that are usually on the extensor surfaces and scalp. "We identified 34 housekeeping genes associated with psoriasis and observed that the co-expression relationships between six genes (APOL2, DCUN1D3, UBE2F, HIGD1A, PPIF, and STAT3) and known psoriasis-related genes differed significantly between diseased and healthy individuals." (PMID 40959079, 2025).
pustular psoriasis (1 paper, 2025). "For instance, the interaction between DCUN1D3 and IL36RN, a key antagonist of IL - 36 receptor signaling, implies a role in modulating IL - 36 dependent epidermal barrier dysfunction, a mechanism recently implicated in pustular psoriasis." (PMID 40959079, 2025).
DCUN1D3 also shares sentences with these, for which no sentence is quoted: Alzheimer disease (1 paper); cancer (1); Parkinson disease (1); tumor (1).